KLRB1 (killer cell lectin like receptor B1)
Diseases named in the same sentence as KLRB1 in open-access papers (continued):
Sharing a sentence is not in itself a finding about the gene and the disease.
cancer (continued). "Additionally, we found that KLRB1 expression levels were significantly down-regulated in the cancer tissues of patients over the age of 65 compared to those of patients aged 65 or younger." (PMID 38782996, 2024). "KLRB1 is considered to influence the development and progression of a number of cancers." (PMID 38608099, 2024). "Likewise, KLRB1 expression levels were significantly down-regulated in the cancer tissues of patients with stage II, III, or IV LUAD compared to those of patients with stage I LUAD." (PMID 38782996, 2024). "Additionally, KLRB1 expression was observed to involve the cancer pathways (such as the NF-κB, PI3K-Akt, and TNF pathways)." (PMID 37988189, 2023). "Furthermore, the results of wound healing and transwell methods revealed that KLRB1 overexpression inhibited cancer cell migration and invasiveness." (PMID 37988189, 2023). "Moreover, KLRB1 expression remained at low levels in the cancer tissues of 113 paired BRCA patients." (PMID 37988189, 2023). "The expression of KLRB1 was downregulated across the majority of cancers including BC." (PMID 37520246, 2023). "We examined the differential expression of KLRB1 in pan-cancer." (PMID 37520246, 2023). "In this study, we used relevant public databases, including TCGA (The Cancer Genome Atlas), GEO (Gene Expression Omnibus), CCLE (Cancer Cell Line Encyclopedia), GTEx (Genotype Tissue-Expression), and HPA (Human Protein Atlas), to perform a pan-cancer analysis of KLRB1 across 33 types of cancer." (PMID 35028320, 2022). "Interestingly, in the 33 cancers evaluated, there was a significant positive correlation between KLRB1 and the checkpoint gene score." (PMID 35028320, 2022). "Further analysis of KLRB1 RNA expression and clinical data from The Cancer Genome Atlas (TCGA) and the Genotype-Tissue Expression (GTEx) indicate that it is upregulated in most human cancers but also downregulated in others." (PMID 35185935, 2022). "The loss 12p13.31 contained the KLRB1 gene encoding the CD161 receptor of NK cells, and it is currently thought that this gene affects tumorigenesis by regulating the cytotoxicity of NK cells in cancer." (PMID 35742955, 2022). "Therefore, we used the GSCALite platform to evaluate the methylation characteristics of KLRB1 and marker genes of T cells and macrophages in TCGA cancers." (PMID 36660546, 2022). "It is noteworthy that KLRB1 expression is significantly correlated with age in 11 cancers, which may contribute to guide clinical treatment options and drug selection." (PMID 35028320, 2022). "Hence, our research is aimed at providing a relatively comprehensive understanding of the role of KLRB1 in different types of cancer, paving the way for further research on the molecular mechanism and immunotherapy potential of KLRB1." (PMID 35028320, 2022). "Patients with high expression of KLRB1 have a better prognosis in most types of cancer." (PMID 35028320, 2022). "Therefore, our study conducted a pan-cancer analysis of KLRB1 in 33 cancers extracting data from multiple databases, including datasets from The Cancer Genome Atlas (TCGA) and the Gene Expression Omnibus (GEO)." (PMID 35028320, 2022). "Our data indicate that KLRB1 is a protective gene in most cancers." (PMID 35028320, 2022). "KLRB1, which encodes CD161, a surface marker on several T cell subsets and NK cells, has been found to be most frequently associated with favorable outcomes in many cancer types by enhancing innate immune characteristics." (PMID 31620363, 2019). "However, further research is needed to confirm the relationship between KLRB1 expression and clinical features, cancer subtypes, and prognosis using clinical tissue samples of BRCA patients, and explore the signaling mechanisms of KLRB1 in BRCA progression in the future." (PMID 37988189, 2023). "Compared to paired normal tissues, the expression levels of KLRB1 and CD163L1 were reduced in cancer tissues." (PMID 39202452, 2024).
cancer (continued). "Low KLRB1 expression correlated with poor RFS in all tumors, infiltrating duct carcinoma, ER (+) cancers, ER (-) cancers, as well as luminal A subtype (all p < 0.05)." (PMID 37520246, 2023). "K-M survival analysis indicated that OS and PFS were better in cancer patients treated with PDCD1, CD274, and CTLA4 with elevated KLRB1 expression." (PMID 37988189, 2023). "KLRB1 is involved in the coding of NKRP1A/LLT1, which triggers the activation of T cells and B cells and can be used in the treatment of cancer, and its interaction with LLT1 can inhibit natural killing (NK) cell cytotoxicity." (PMID 35090432, 2022). "In addition, the interactions of KIR2DL3 and FAM3C, and KLRB1 and CLEC2D were detected between cancer cells and T & NK cells." (PMID 37945567, 2023). "Additionally, IC50 of the mentioned anti-cancer drugs, especially Nelarabine, is highly positively correlated with the expressions of CD2, ZNF683 and KLRB1, which means drug resistance." (PMID 36090993, 2022). "There is no understanding of the shared or differing roles of KLRB1 in different types of cancer from the perspective of pan-cancer." (PMID 35028320, 2022). "The skin/cancer-related genes in the most significant focally amplified regions worth mentioning are STIM2 (chr4p15.2; q=0.16; occurring in 2 samples), KLRB1/CD161 (chr12p13.31; q=0.007; occurring in 2 samples), and SPTLC3 (chr20p12.1 q=0.23; occurring in 2 samples)." (PMID 34900699, 2021). "In 8 cancers, correlations between KLRB1 and MSI were also negative." (PMID 35028320, 2022). "Additionally, In the cancer patients treated with anti-PDCD1 (Pembrolizumab), anti-CD274 (Atezolizumab), or anti-CTLA4 (Ipilimumab) of the K-M plotter database, elevated KLRB1 expression exhibited better OS and progression-free survival (PFS) after grouping with KLRB1 expression median value." (PMID 37988189, 2023). "There was a negative correlation between the expression of KLRB1 and MSI in 8 tumors, including LIHC, LUSC, and other cancers." (PMID 35028320, 2022).
infection (29 papers, 2012 to 2026). The state of being infected such as from the introduction of a foreign agent such as serum, vaccine, antigenic substance or organism. "After infection with KLRB1 lentivirus, we verified KLRB1 overexpression in MCF7 and MDA-MB-231 cells, confirming that BC cell lines stably expressing KLRB1 were constructed." (PMID 37351109, 2023). "Conversely, the KLRB1+ cluster (cytokine-producing cluster), enriched for cytokine/chemokine genes (CCL5, IFNG, IL32), were depleted during infection." (PMID 41544143, 2026). "The DEG analysis showed that LAIR2, CD7, KLRB1, TYROBP, TRAV19, TRAV21, and TRBV6-5 were upregulated in group E VS group B both breakthrough infection by BA.5.2." (PMID 39835127, 2024).
hematological malignancies (3 papers, 2018 to 2025). "KLRB1 expression, but not PD‐1 expression, correlates with TRM exhaustion, suggesting that KLRB1 may deliver a broad inhibitory signal to CD8+ TRM in hematological malignancies." (PMID 40855628, 2025).
KLRB1 also shares sentences with these, for which no sentence is quoted: Crohn disease (12 papers); juvenile idiopathic arthritis (8); bacterial infections (7); HIV-1 infection (7); asthma (6); co-infection (6); infectious disease (6); prostate carcinoma (6); Arthritis (5); inflammatory bowel disease (5); chronic hepatitis (4); CMV infection (4); hepatitis C (4); Hypertension (4); latent infection (4); multiple myeloma (4); pancreatic ductal adenocarcinoma (4); triple-negative breast carcinoma (4); cardiovascular disease (3); chronic hepatitis B virus infection (3); chronic hepatitis C (3); colon adenocarcinoma (3); colorectal cancer (3); head and neck squamous cell carcinoma (3); immune dysfunctions (3); lupus (3); mesothelioma (3); oropharyngeal squamous cell carcinoma (3); primary progressive multiple sclerosis (3); psoriatic arthritis (3).
A further 127 diseases each share a sentence with KLRB1 in 3 papers or fewer.